PARP1 (poly(ADP-ribose) polymerase 1)
Diseases named in the same sentence as PARP1 in open-access papers (continued):
Sharing a sentence is not in itself a finding about the gene and the disease.
infection (continued). "Our regression analyses suggest that PARP1 activity may promote M.tb infection during the acute phase but enhance M.tb containment during the chronic phase of infection." (PMID 38071218, 2023). "Cells were fixed at indicated time points post infection and stained with PARP-1 antibody." (PMID 36146855, 2022). "Interestingly, we observed a significant increase of caspase-3/pro-caspase-3 ratio (1.5 fold ± 0.19) after infection and a decrease of 89 kDa PARP-1 fragment after infection." (PMID 35765029, 2022). "Research on the involvement of PARP-1 in bovine intramammary infection is limited." (PMID 33803196, 2021). "PARP1 plays important roles in infections of viruses with DNA genome." (PMID 35095818, 2021). "Our study revealed that PARP-1 accumulates in host chromatin 1 h, 6 h, and 72 h post-infection." (PMID 33826673, 2021). "Sindbis virus (SINV), belonging to the Alphavirus, activates PARP1 during infection." (PMID 35095818, 2021). "S. negevensis could block programmed cell death until day 3 post infection, after which point the infection promoted cell death, reflected in the increased PARP1 cleavage." (PMID 33194844, 2020). "Another NAD+-dependent enzyme to have been studied in lytic infection is Poly (ADP-Ribose) Polymerase 1 (PARP1); the AdV E4orf4 protein has been found to increase production of viral progeny through inhibition of PARP1, which is activated by the infection-induced DNA damage response (DDR)." (PMID 31864392, 2019). "However, although PARP1 localized to the nucleus throughout infection, it only colocalized with the viral nucleoprotein early in infection in cells expressing abundant NP distributed throughout the nucleoplasm." (PMID 31015836, 2019). "Results showed that infection with Ad-PARP1 resulted in up-regulation of Gabarapl1, ATG12 and LC3." (PMID 30323296, 2018). "In PARP1-/- mice, PARP1 mRNA and protein levels remained undetectable before or after Tc infection." (PMID 29851986, 2018). "PARP1 was then specifically knocked down by infection of shPARP1 in MI mice." (PMID 30323296, 2018). "We then carried out silencing of Parp1 or Parp2 by infection with shRNA-expressing lentiviruses." (PMID 28095779, 2017). "PARP-1 inhibition was capable to lessen HIV replication in MDM by 60–80% after 7 days infection." (PMID 26379653, 2015). "However, in untreated cells, PARP-1 is present in the native state at 24 h post-infection and in the native and cleaved state at 48 and 72 h post-infection." (PMID 25614100, 2015). "Furthermore, Western blot analysis demonstrated that at later periods of infection there was a marked proteolysis of PARP-1, a nuclear enzyme whose cleavage into a 85-kDA fragment by caspase-3 confirms that cells are undergoing apoptosis." (PMID 24490870, 2014). "We envisage that these results might lead to consider PARP-1 inhibitors as potential therapeutic agents to control the spread of EBV productive infection." (PMID 17931416, 2007). "Similarly, siRNA-mediated knockdown of CTSS in A549 cells led to decreased production of proinflammatory cytokines, reduced cleavage of the apoptotic marker PARP1, and preserved E-cadherin expression, thereby maintaining tight junctions and epithelial barrier function during infection." (PMID 41258714, 2026). "Infection with adenovirus encoding shRNA against c-Jun (shc-Jun), but not against p65 (shp65), abolished PARP1 overexpression-induced upregulation of CyclinD1, Pcna, Mmp9, Pxn, Spp1 and Tnc genes, suggesting that c-Jun mediated the effects of PARP1 on VSMC proliferation and migration." (PMID 40744995, 2025). "Finally, we evaluated the activity of PARP1 and found a substantial increase in the levels of pADPr-modified proteins in Citrobacter-infected mice by western blot, indicating that infection with C. rodentium induces PARP1 activity." (PMID 37744380, 2023).
infection (continued). "Indeed, after infection, we observed, with both siRNAs, a significant increase of caspase-9 (to about 1.5 fold ± 0.03 and 1.3 fold ± 0.04) and of 89 kDa PARP-1 fragment (to about 2.7fold ± 0.21 and 7.6fold ± 0.23) compared to infected scrambled cells, used as a control." (PMID 35765029, 2022). "Moreover, infection with Ad-PARP1 vs. empty vectors increased autophagosome accumulation." (PMID 30323296, 2018). "Compared with the control group, the Pm challenge group showed significantly increased PARP1, HMGB1, IL-1β, and IL-18 protein expression in the blood vessels, indicating that Pm infection in mice triggered vascular inflammatory injury." (PMID 39850582, 2024). "It was found that the expression of PARP1 mRNA and accumulation of PARylated proteins were significantly suppressed by PVX-NbPARP1 infection (starting at 7 dpi) compared with control plants infected with PVX-C." (PMID 37376582, 2023). "Heightened levels of PARP1, WARS and KYNU are predictive at the acute stage of infection for resilience, while in contrast, levels remained high and are predictive of persistent and more severe outcomes in COVID disease." (PMID 36499104, 2022). "In our study, we found that infection of PSV triggered significant cell apoptosis, where chromatin condensation, nuclear fragmentation, phosphatidylserine (PS) eversion, and PARP1 degradation occurred." (PMID 36505441, 2022). "We also investigated the mRNA relative expression of PARP-1, OGG1, and XRCC1, a protein involved in repairing DNA single-strand breaks, after 6 h of infection." (PMID 33826673, 2021). "Consistent with its potential role in DDR during infection, our previously published SIRT2 interactome identified many DNA damage sensor and repair proteins including KU70/KU80, RPA1, FEN1 and PARP1." (PMID 34929015, 2021). "Instead, it appears that PARP1 and SIRT1 balance the Mo/Mφ role for removal of cellular debris produced by Tc infection and prevent further tissue damage while promoting healing." (PMID 31905606, 2019). "PARP1 was cleaved and the levels of cleaved PARP1 significantly increased in a time-dependent manner following SVV infection." (PMID 31191506, 2019). "In the absence of zVAD-FMK, a key signature of apoptotic induction was observed by 4 hours post-infection, namely cleavage of the activated caspase substrate poly(ADP-ribose) polymerase 1 (PARP1)." (PMID 30142213, 2018). "In mock infected cells also there was a detectable PARP-1 cleavage at 96h p.i. consistently present in the multiple experiments we carried out, indicating a mild degree of apoptosis which could be attributed to low serum (2%) in the medium in which the cells were grown post-infection." (PMID 24086645, 2013). "Here, infection with Ad-PARP1 suppressed myocardin or myocardin–SRF overexpression-induced luciferase activities driven by WT-SM22α, indicating that overexpression of PARP1 suppressed myocardin–SRF-dependent promoter activation." (PMID 40744995, 2025). "In support of this, infection with Ad-PARP1 decreased myocardin–c-Jun coprecipitates, but infection with Ad- mut-PARP1 did not." (PMID 40744995, 2025). "Two additional PZA-treated mice (25%) had low PAR levels but bacterial burdens higher than the vehicle average, supporting that PARP1 inhibition alone is not sufficient to clear the infection." (PMID 38071218, 2023). "Again, IFN-β induction by adenovirus was markedly reduced in PARP1-deficient cells or non-cleavable PARP1 (D214N)-expressing cells, suggesting that PARP1 cleavage promotes IFN-β expression and apoptosis during pathogen infection." (PMID 35039483, 2022). "TNF-α plus cycloheximide (CHX) treatment triggered autocleavage of caspase-8 as well as its cleavages of Bid, caspase-3, caspase-7, and PARP1, all of which was blocked by infection with CopC-positive C. violaceum but not ΔcopC strain." (PMID 35446120, 2022). "In addition, the cleaved fragment of DNA repair enzyme PARP1, a substrate for caspase-3, increased with the dose of PSV infection." (PMID 36505441, 2022).
infection (continued). "During infection, CopC I55D/F58D/L59D, complemented into the C. violaceum ΔcopC, also failed to block TNF-α-plus-CHX stimulation of the apoptotic program in HeLa cells, evident from the diminished cleavage of caspase-3, caspase-7, and PARP1." (PMID 35446120, 2022). "The results showed that tBid-induced caspase-9 activation, as well as its cleavages of caspase-3, caspase-7, and PARP1, was blocked by CopC-positive C. violaceum but not the ΔcopC infection." (PMID 35446120, 2022). "This highlights a common theme where PARP1 plays several protective roles in the infection, both dependent and independent of its catalytic activity." (PMID 34871367, 2021). "Furthermore, purpose for PARP-1 in driving infection is found by the function of the IAV RNA-Dependent RNA polymerase, which is dependent on PARP-1." (PMID 34485381, 2021). "At the same time, in non-treated infected samples we observed an increase in PARP1 cleavage on day 4 post infection, indicating cell death induction by S. negevensis at this point." (PMID 33194844, 2020). "Moreover, the PARP-1 cleavage, TUNEL and agarose gel electrophoresis assays showed that Wt1-5 infection was an inducer of DNA fragmentation, a key feature of apoptotic cell death." (PMID 32722005, 2020). "Albeit to a lesser extent compared to LNA-1285 treatment, infection of both SW480 and CR-CSCs with this construct significantly impaired cell proliferation and capacity to generate colonies in soft agar, leading to apoptosis as indicated by PARP-1 cleavage." (PMID 32244500, 2020). "We observed that S. negevensis effectively blocked TNFα-induced PARP1 cleavage on day 3, but not on day 4 post infection." (PMID 33194844, 2020). "A mild, transient loss of PARylation activity at early timepoints was not significant, as variation in cellular PARP1 protein abundance was evident through the course of infection." (PMID 31015836, 2019). "However, IMPDH2 that interacts with and supplies PARP1 and PARP2 with NAD+ substrates for enzymatic reactions significantly enhances polymerase activity during infection." (PMID 31015836, 2019). "Treatment of HeLa cells with 50 μM H2O2 did not enhance POLG/PARP1 interaction to the same extent as was noted with Tc infection." (PMID 29851986, 2018). "In contrast to the paradigm in mammals, we found that PARP2 rather than PARP1 plays the major role biochemically and in organismal-level responses to DNA damage and pathogen infections." (PMID 25950582, 2015). "Cleaved PARP-1 levels did not rise after infection with AAV, whereas they increased significantly after ActD-mediated apoptosis." (PMID 21853057, 2011). "PARP1 cleavage became significantly augmented between 6 and 12 h p.i., but a twofold increase, although not statistically significant, was identified 1 h after infection." (PMID 37834296, 2023). "For mild disease (no hospitalizations), marker levels of KYNU, WARS and PARP1, ascertained at the acute stage of infection could distinguish a more severe outcome using ROC." (PMID 36499104, 2022). "Surprisingly, when we applied STS as an inducer of cell death, we saw that S. negevensis could not inhibit PARP1 cleavage neither on day 3, nor on day 4 post infection." (PMID 33194844, 2020). "Together, our findings suggest that PARP1 activation may promote bacterial expansion in the acute phase of infection but contribute to bacterial containment during the chronic phase of infection, indicating that PARP1 inhibition without effective antibiotics may antagonize bacterial clearance." (PMID 38071218, 2023). "We also observed increased levels of cleaved PARP1 in WT and GSDMD KD cells after infection indicating that cell death induced by infection was not broadly prevented by GSDMD depletion, though lactate dehydrogenase release was decreased in GSDMD KD cells." (PMID 38553499, 2024). "Moreover, PRV-ΔUL10 infection could not activate caspase-3/7 and cleave PARP1 in HeLa cells." (PMID 38669242, 2024).
infection (continued). "Here we show that Arabidopsis PARP2 rather than PARP1 plays the predominant role in poly(ADP-ribosyl)ation and organismal resilience in response to either chemically-induced DNA damage or pathogen infections." (PMID 25950582, 2015). "Therefore, we measured PARP-1 expression in the nuclei of cells infected with AN5; the results indicate that PARP1 does not have a differential expression due to infection." (PMID 30021619, 2018). "Additionally, HSV-1 infection also activated caspase-3/7 and cleaved PARP1 in HeLa cells, as well as induced caspase-3/7/9 activation in THP-1 cells, while HSV-1-ΔUL10 infection could not." (PMID 38669242, 2024).
neurodegenerative disease (67 papers, 2012 to 2025). A disorder of the central nervous system characterized by gradual and progressive loss of neural tissue and neurologic function. "PARP-1 activity was also associated with multiple sclerosis (MS), another inflammatory-neurodegenerative disease." (PMID 31877876, 2019). "We summarize recent data on the proteins involved in DNA repair associated with neurodegenerative diseases, with particular emphasis on PARP1 and ND-associated proteins, which are involved in DNA repair and have the ability to undergo liquid–liquid phase separation." (PMID 39767715, 2024). "Overactivation of PARP-1 and parthanatos has been implicated in the development of various neurodegenerative diseases, and therefore suppression of parthanatos is thought to be a potential therapeutic strategy for neurodegenerative diseases." (PMID 37060999, 2023). "For example, inhibition of PARP1 has been shown to alleviate neuronal damage in models of neurodegenerative diseases and ischemic injury, highlighting the importance of this pathway in therapeutic interventions." (PMID 41460301, 2025). "Another NAD+-consuming enzyme, PARP1, has long been thought to be involved in PD and other neurodegenerative diseases." (PMID 39824831, 2025). "In neurodegenerative diseases, overactivation of PARP1 mediates neuroinflammation and triggers energy-exhausting cell death, and abnormal PARylation accelerates toxic protein aggregation." (PMID 41460301, 2025). "This, in turn, triggers PARP1‐mediated cell death, followed by subsequent neuroinflammatory responses, finally exacerbating neurodegenerative disease progression." (PMID 40904702, 2025). "In contrast, excessive PARP1 activation drives neuronal death in neurodegenerative diseases and metabolic dysfunction in diabetes." (PMID 40904702, 2025). "The last interesting candidate is PARP1 which generally plays a crucial role in DNA repair pathway, a process that is disrupted in multiple neurodegenerative diseases, including HD." (PMID 39604147, 2024). "Continuous oxidative stress and PARP-1 activation are present in neurodegenerative diseases such as PD, and PARP-1-mediated parthanatos is one of the main forms of neuronal death in this disease." (PMID 38476326, 2024). "Despite the neuroprotective potential of RSV as a SIRT1 activator and PARP1 inhibitor, the low oral bioavailability of this polyphenol has limited its use as an effective drug to treat neurodegenerative diseases." (PMID 38397799, 2024). "PARP-1 is involved in the pathogenesis of various neurodegenerative diseases and is regulated during demyelination as well as remyelination." (PMID 37525026, 2023). "Within the PARP family, PARP-1 is the best-characterized member and its excessive activation has been connected with neurodegenerative diseases and a particular form of cell death, termed PARthanatos." (PMID 37189329, 2023). "In particular, it was observed that PARP1 is activated in aging and neurodegenerative diseases leading to autophagy, neuroinflammation and mitochondrial dysfunction and dysregulation." (PMID 36399449, 2022). "This suggests a possible inverse comorbidity between tumors and neurodegenerative diseases in which the PARP1 gene is among the protagonists." (PMID 35741059, 2022). "Taken together, these pre-clinical reports provide strong evidence for the utility of PARP-1 inhibitors in neurological disorders, neuroinflammation, and neurodegenerative diseases." (PMID 35158955, 2022). "In vivo or in vitro experiments have demonstrated the expression and activity of PARP1 in pathological sites is related to the development of neurodegenerative diseases." (PMID 36438061, 2022). "Studies carried out on PARP1 gene expression show that the PARP1 protein tends to be overexpressed in many tumors; on the contrary, the same PARP1 protein is underexpressed in neurodegenerative diseases, such as PD." (PMID 35741059, 2022).